INS (insulin)
Diseases named in the same sentence as INS in open-access papers (continued):
Sharing a sentence is not in itself a finding about the gene and the disease.
diabetes (continued). "The purpose of this study was to assess changes in quality of life (QOL) associated with switching the basal insulin regimen to degludec in patients with type 1 and type 2 diabetes mellitus." (PMID 26819737, 2015). "The polymorphism rs13266634 (C > T), which causes R325W amino acid substitution, predisposes to diabetes impairing the proper insulin secretion and unbalancing the pro-insulin / insulin equilibrium in favour of pro-insulin." (PMID 26559814, 2015). "In a population-based study, betel nut chewing has been associated with an increase in serum insulin levels and a higher risk of type 2 diabetes mellitus." (PMID 25695047, 2015). "In keeping with previous reports, a high fat diet followed by a single dose of STZ resulted in increased plasma glucose and reduced plasma insulin secretion, coupled with a marked increase in water intake and HbA1c, characteristics associated with diabetes." (PMID 25759824, 2015). "In animals, dwarf, long-lived mice lacking the growth hormone receptor (GHR-/-) have reduced levels of IGF-1, are insulin sensitive despite obesity, and have decreased risk for cancer and diabetes." (PMID 25902704, 2015). "Type 2 diabetes mellitus (T2DM) results from progressive increases in insulin resistance—a hindered biological response to insulin—coupled with a progressive loss of beta cell function and/or mass." (PMID 25742416, 2015). "Regarding predictors for hypoglycemia, insulin use and intensive therapy are most consistently and strongly associated with risk for severe hypoglycemia in patients with diabetes." (PMID 26102197, 2015). "Individual differences in sensitivity to insulin contribute to disease susceptibility including diabetes and metabolic syndrome." (PMID 26202599, 2015). "Lower adiponectin among Mexican Americans was associated with lower insulin sensitivity which is a known risk factor for diabetes." (PMID 26703682, 2015). "According to major research, amylin or IAPP is a pancreatic peptide hormone naturally produced with insulin and appears to be involved in the cause of both main types of diabetes." (PMID 26582441, 2015). "Diabetes mellitus is a metabolic disease which is caused by impaired insulin production and/or decreased tissue response to the insulin, and is characterized by elevated blood glucose." (PMID 25889508, 2015). "STZ administration affected the levels of typical blood parameters characteristic for diabetes, which are also accepted values in diabetes diagnostic (glucose, insulin and HbA1c)." (PMID 25652875, 2015). "The higher 2-hour insulin levels and lower insulin sensitivity seen in Ala12 allele carriers is in contrast to the majority of previous studies, where the risk of diabetes has been shown to decrease with each additional Ala12 allele." (PMID 25974167, 2015). "A previous study suggested a possible association between 3’-UTR markers and diabetes mellitus type 2, an association of possible relevance owing to evidence showing that insulin signaling is down-regulated in AD." (PMID 26626881, 2015). "Insulin-treated diabetes is associated with poor functional recovery and increased mortality in patients with advanced HF after CRT." (PMID 25880202, 2015). "Sleep disturbances and, particularly, deprivation are associated with an increased risk of obesity, diabetes and insulin insensitivity, and dysregulation of leptin and ghrelin, which negatively impact human health." (PMID 25861266, 2015). "Diabetes mellitus (DM) is a chronic disease characterized by high blood glucose levels caused by either insufficient insulin production by the pancreas or improper response of the body cells to insulin." (PMID 26448950, 2015). "Diabetes and pre-diabetic states, characterized by impairments in glucose, insulin and insulin sensitivity, are known to be risk factors for cognitive decline, mild cognitive impairment and dementia." (PMID 26178969, 2015).
diabetes (continued). "Diabetes mellitus is associated with the altered expression of several miRNAs in insulin-target tissues, as well as in insulin-secreting cells." (PMID 25888955, 2015). "25OHD deficiency within individuals is associated with an increased risk of type 2 diabetes mellitus, possibly via influence on beta cell function and insulin sensitivity." (PMID 26244505, 2015). "The goal of these studies was to identify novel targets of insulin action relevant to the development of diabetes-associated CVD." (PMID 25849138, 2015). "Diabetes mellitus can be caused by multiple factors that include hyperglycemia, decreased insulin concentrations or its sensitivity." (PMID 27047315, 2015). "This painstaking approach revealed the direct influence of a subset of diabetes risk loci on impaired insulin secretion ex vivo, and provided mechanistic insights into the role of these genetic variants." (PMID 25982967, 2015). "Insulin plays an important role in fetal growth and elevated insulin is associated with development of obesity and diabetes." (PMID 26561832, 2015). "Insulin and diabetes have been connected to an increased risk of developing AD and cognitive impairment." (PMID 26379621, 2015). "Type 1 diabetes mellitus (T1DM) is an autoimmune disorder caused by the selective destruction of insulin-producing β cell." (PMID 26358493, 2015). "Increased levels of Reg Iα in response to β-cell damage has been associated with β-cell regeneration and increase in their insulin secretory capacity, leading to better control of diabetes and its associated risk factors." (PMID 26568772, 2015). "The diabetes-related treatment cost was lowest using NPH insulin but only premixed insulin was associated with higher diabetes-related health care costs than NPH." (PMID 28702235, 2015). "The Bogalusa Heart Study showed childhood glucose and insulin concentrations to be predictive of adult diabetes and CVD risk factors." (PMID 25940643, 2015). "The present study reveals a significantly higher risk of breast cancer associated with prolonged use of human insulin in female patients with type 2 diabetes mellitus." (PMID 26537234, 2015). "In earlier studies, several factors like age, duration of diabetes, hypertension (HTN), smoking, gender, obesity, family history of diabetes, dyslipidemia, poor control of diabetes, insulin use, neuropathy and nephropathy were shown to be associated with DR." (PMID 26644890, 2015). "The MDC Study in Sweden showed a significant positive association between copeptin and incident diabetes even after adjustment for fasting insulin and fasting blood glucose." (PMID 26158609, 2015). "Diabetes is a complex metabolic disorder triggered by the deficient secretion of insulin by the pancreatic β-cell or the resistance of peripheral tissues to the action of the hormone." (PMID 25995968, 2015). "In this work, we examined the change in QOL associated with a switch in basal insulin regimen from glargine or detemir to degludec in patients with type 1 and type 2 diabetes mellitus." (PMID 26819737, 2015). "Type 2 diabetes mellitus is characterized by the loss of sensitivity to insulin, thus improving insulin resistance is an effective strategy to treat type 2 diabetes mellitus." (PMID 26690098, 2015). "It was observed that the outcome of diabetes in Fenugreek group was positively associated with serum insulin (OR 1.98, 95 % CI 1.30–3.02; p < 0.01) and negatively associated with HOMA IR (OR 0.07, 95 % CI 0.02–0.30; p < 0.001)." (PMID 26436069, 2015). "In these high-risk ICU patients, both diabetes-specific formulas lowered insulin requirements, improved glycemic control and reduced the risk of acquired infections relative to the standard formula." (PMID 26549276, 2015). "Although the causal link between diabetes and changes in astrocyte function is yet to be fully elucidated, insulin is known to regulate both the differentiation and function of astrocytes." (PMID 25759824, 2015).
diabetes (continued). "For example, the insulin-sensitizing effects of PF can cause severe hypoglycemia and even death in patients with diabetes treated with insulin." (PMID 25902704, 2015). "Several studies have shown that the significance of insulin resistance and insulin secretion defect to diabetes development is linked to patients’ race." (PMID 25924608, 2015). "Diabetes mellitus is the most common endocrine disorder disease caused by inherited or acquired deficiency in insulin excretion and by decreased responsiveness of the organs to secreted insulin." (PMID 25767553, 2015). "Type 2 diabetes mellitus causes high glucose levels in the blood due to enhanced liver glucose production, or “insulin resistance” (insensitive response to insulin by peripheral tissues)." (PMID 26492243, 2015). "Treatment with insulin efficiently ameliorated the histopathological disorders caused by diabetes in these animals." (PMID 26185997, 2015). "Diabetes mellitus is manifested with chronic hyperglycemia, impaired lipid and disturbed protein metabolism, due to deficiency of insulin secretion and/or insulin resistance in peripheral tissues." (PMID 26176625, 2015). "Adiponectin is a major contributor in insulin sensitivity and in decreasing the risk of diabetes and coronary heart diseases." (PMID 26482904, 2015). "Diabetes mellitus, as a multi-factorial disease, is characterized by chronic hyperglycemia due to insulin resistance and defect in insulin secretion and/or insulin action caused by Langerhans islets β-cell failure." (PMID 26131436, 2015). "It was reported that elevated copeptin predicts increased risk for diabetes mellitus independently of fasting glucose and insulin." (PMID 26566413, 2015). "Nevertheless, female rats are less sensitive to insulin than male rats and more susceptible to the severe form of diabetes." (PMID 26110898, 2015). "In the adjusted analysis age, diabetes duration and being under insulin treatment were associated with diabetic retinopathy." (PMID 25925666, 2015). "The ectopic storage of lipids has been identified as a major cause of diabetes, and the excess storage of lipids in skeletal muscle significantly influences its insulin sensitivity." (PMID 26942218, 2015). "Our results indicated that prophylactic insulin therapy in SENP1-deficient mice at the age of 5 weeks for 9 weeks only partially ameliorates development of diabetes phenotypes including immune cell infiltration, β-cell apoptosis and islet disruptions." (PMID 26596471, 2015). "STZ has highly selective toxic effects on islet cells in experimental animals, which leads to direct destruction of pancreatic β cells of the islet tissue or causes an immune response and decreases the insulin secretion of islets, which leads to diabetes." (PMID 25847066, 2015). "It is the production of inflammatory cytokines (IL-1 and TNF) that contribute to the loss of insulin producing β-cells and diabetes development." (PMID 26295266, 2015). "Diabetes is associated not only with defects in insulin action, but also with multiple other changes in the hormonal milieu." (PMID 25849138, 2015). "It has been suggested that duration of diabetes and use of exogenous insulin were associated with the cancer risk." (PMID 26541196, 2015). "Human subjects with nocturnal life (consuming majority of their calories just before overnight sleep) showed weakened association between glucose elevation and insulin secretion, which is likely to be a risk factor of obesity and diabetes." (PMID 25861266, 2015). "Diabetes mellitus (DM) is a multifactorial disease characterized by hyperglycemia and glucose intolerance due to insulin deficiency, impaired effectiveness of insulin action, or both." (PMID 25898207, 2015). "Hyperglycemia resulting from defects in insulin secretion, insulin action, or both, is considered the main cause of the debilitating effects of diabetes." (PMID 26205060, 2015).
diabetes (continued). "In support of a regular insulin therapy, physical activity and exercise training have shown to positively affect patients with type 1 diabetes mellitus (T1DM) reducing the risk of all-cause mortality and cardiovascular disease and cancer." (PMID 26317981, 2015). "Diabetes refers to a metabolic disorder characterized by relative or absolute deficiency of insulin secretion and/or insulin resistance." (PMID 25821809, 2015). "Diabetes is a serious disease characterized by insufficient insulin secretion, insulin activity deficiency and hyperglycemia, and its estimated prevalence is pretty high (5.4% in 2025) in society." (PMID 27275196, 2015). "ERα knockout mice have increased susceptibility to oxidative stress, precipitating beta cell apoptosis and insulin-deficient diabetes." (PMID 25883987, 2015). "The relative or absolute deficiency of insulin secretion is an important factor in the development of diabetes." (PMID 26942221, 2015). "Diabetes mellitus is characterized by disrupted glucose homeostasis due to loss or dysfunction of insulin-producing beta cells." (PMID 26384018, 2015). "Oxidative stress has been implicated in the onset and development of impaired insulin secretion and insulin resistance, the two main mechanisms involved in diabetes." (PMID 25821809, 2015). "Diabetes is triggered by the deficient secretion of insulin by the pancreatic β-cell (T1D) or the resistance of peripheral tissues to the action of this hormone (T2D)." (PMID 25995968, 2015). "A hallmark feature of type 1 and type 2 diabetes mellitus is the progressive dysfunction and loss of insulin-producing pancreatic beta cells, and inflammatory cytokines are known to trigger beta cell death." (PMID 26422139, 2015). "Type 1 diabetes mellitus is caused by cell-specific autoimmune destruction of the insulin producing beta cells in the pancreas." (PMID 25821809, 2015). "The outcome of diabetes in Fenugreek group was positively associated with serum insulin and negatively associated with insulin resistance (HOMA IR)." (PMID 26436069, 2015). "Recent experiments showed that a CTB-insulin vaccine that induced tolerance to diabetes autoantigens in humans is linked to inhibition of DC maturation." (PMID 26378585, 2015). "PTBP1 plays a pivotal role in the mRNA stabilization and translation of insulin in the pancreas and it has been associated with diabetes." (PMID 26566043, 2015). "In the San Antonio Heart Study, MetS predicted the incident rate of diabetes (11.3%) independently of other risk factors such as fasting insulin and impaired glucose tolerance during a 7- to 8-year follow-up in 1,734 participants." (PMID 26000038, 2015). "In mouse models of obesity, differences in beta-cell adaptation to increased insulin demand are due to an underlying genetic background causing either diabetes susceptibility or resistance." (PMID 26348837, 2015). "Given that pregnancy itself has a diabetogenic effect due to a decrease in insulin sensitivity of maternal tissues and resultant increase in insulin demand, pregnant sows would theoretically be even more susceptible to develop diabetes upon cyanide exposure." (PMID 26101526, 2015). "Diabetes mellitus (hyperglycemia), a metabolic disorder, is caused either due to lower insulin secretion by the cells or due to lower binding efficiency of insulin on their cell surface receptors resulting in high blood glucose level." (PMID 26498972, 2015). "Type 2 diabetes mellitus (T2DM) has two major characteristics: reduced insulin sensitivity linked to obesity and impaired insulin secretion due to β-cell dysfunction." (PMID 26351642, 2015). "We verified that the chronic consumption of aqueous extract reduces the inflammatory infiltrate index in pancreatic islets, maintaining serum insulin levels and hepatic glutathione, and reducing serum lipid peroxidation as well as the risk for diabetes." (PMID 26783951, 2015).
diabetes (continued). "Diabetes mellitus (DM) is a chronic metabolic disorder caused by either absolute deficiency in insulin secretion or reduction in the biological effectiveness of insulin." (PMID 26504482, 2015). "The rsT2DM had the greatest improvement in insulin sensitivity which was associated with remission of diabetes." (PMID 25742416, 2015). "Defects in genes that encode proteins affect pathways involved in insulin control and glucose homeostasis (the balance of insulin and the hormone glucagon to maintain blood glucose), hence can raise the risk for diabetes." (PMID 26334876, 2015). "In this context, mounting evidence indicates that impaired glucose metabolism, insulin signaling and diabetes are associated with PD." (PMID 26566043, 2015). "The strong polygenic pleiotropy between lipids and T1D also supports a role of lipid pathobiology, as shown in relation to insulin secretion, diabetes risk and pathology." (PMID 25853426, 2015). "Due to the possible link between hypoglycaemia and dementia, it is useful to balance the need for treatment with insulin and sulphonylureas and the risk of developing hypoglycaemia in patients who have diabetes and dementia." (PMID 26193295, 2015). "It has been noticed that, in individuals with an increased risk of developing obesity and diabetes, there are too many α2A-adrenoceptors in beta cells in the pancreas, which impairs proper insulin release and leads to hyperglycemia." (PMID 26506439, 2015). "The outcome of this study indicates that the consumption of large amounts of a food naturally enriched in CLAt10,c12 content can significantly impair whole body glucose and insulin tolerance in a diabetes-susceptible rodent model." (PMID 26415741, 2015). "PDK4 was first identified in a linkage study of loci associated with Type 2 diabetes mellitus in Native Americans, and insulin is known to repress PDK4 transcription." (PMID 26576332, 2015). "In vivo studies on partially insulin-deficient rats, demonstrated that diabetes induced deleterious changes on long-bone micro-architecture." (PMID 25668621, 2015). "Our data suggest two potential therapeutic strategies for mitigating the heart disease burden associated with states of elevated insulin (e.g., pre-diabetes or T2DM)." (PMID 26682540, 2015). "The aim of this study was to examine the prospective association between copeptin and the risk of diabetes in older men and assess the role of insulin and inflammation and endothelial dysfunction in the association." (PMID 26158609, 2015). "Another two studies, in different countries, showed that insulin use and diabetes-related complications were significantly associated with poorer QoL." (PMID 26666403, 2015). "A case in point are genetic polymorphisms in the insulin signaling pathway with demonstrable effects on diabetes and other diseases." (PMID 25774510, 2015). "Our observation of the opposite effects of simvastatin and pravastatin on glucose-stimulated insulin secretion is in agreement with previous reports showing that simvastatin, but not pravastatin, was associated with an increased risk of incident diabetes." (PMID 26561346, 2015). "Based on the results of the current study, a prospective characterisation of the time-course of the loss of the insulin secretory capacity and the comparison with other diabetes types would require a multi-centre study with long-term follow-up." (PMID 25572256, 2015). "Three percent (n = 4) had HbA1c-values indicative of increased risk of diabetes mellitus and 82% (n = 129) were insulin resistant as defined by elevated HOMA-index for age." (PMID 26694031, 2015). "The impact of the diabetes risk G-allele of FAF1-rs17106184 on increased 2-hour insulin levels is however unexplained." (PMID 25799151, 2015). "For a sub-group of adolescents who were on intensive insulin regimens, higher levels of caregiver health literacy were associated with greater adherence to the diabetes management scale (p < 0.01) (quality rating IIIC)." (PMID 26242306, 2015).